METTL3 (methyltransferase 3, N6-adenosine-methyltransferase complex catalytic subunit)
Diseases named in the same sentence as METTL3 in open-access papers (continued):
Sharing a sentence is not in itself a finding about the gene and the disease.
renal fibrosis (continued). "PLGA-encapsulated Levosimendan not only alleviates repeated low-dose CDDP-induced renal fibrosis, but also significantly enhances the chemotherapeutic effects of cisplatin in several xenograft and syngeneic mouse tumor models by suppressing the Mettl3/Pfkfb3/lactate/ H3K18la/PD-L1 axis." (PMID 40765834, 2025). "Thus, the Mettl3/Pfkfb3/lactate/ H3K18la/PD-L1 axis regulates renal fibrosis induced by low-dose cisplatin." (PMID 40765834, 2025). "Similarly, METTL3 was found to fulfill a pivotal catalytic role in m6A modification in renal fibrosis, instigating obstructive renal fibrosis by promoting the maturation of miR-21-5p, consequently activating the SPRY1/ERK/NF-kB signaling pathway." (PMID 39756462, 2025). "Meanwhile, the overactivated METTL3/EVL m6A axis is a potential target for renal fibrosis therapy, which maybe be an important upstream of the regulation of GSDME." (PMID 38388468, 2024). "Together, these results suggest that METTL3 is a key mediator of renal fibrosis." (PMID 37537731, 2023). "Moreover, METTL3 cKO in the kidneys and silencing in HK‐2 cells not only attenuated renal fibrosis induced by UUO and I/R but also reduced TGF‐β1‐ and H/R‐induced fibrotic responses." (PMID 37537731, 2023). "To evaluate the influence of METTL3‐dominated m6A modification on renal fibrosis, we performed relevant experimental studies using Ksp‐Cre‐METTL3 (Flox/Flox) conditional knockout (cKO) mice and small interfering RNA (siRNA)‐silenced renal tubular epithelial cells (HK‐2)." (PMID 37537731, 2023). "METTL3 contributes to the development of renal fibrosis by promoting inflammation." (PMID 37671161, 2023). "This study identified a novel TCM monomer inhibitor and provided evidence suggesting that it may be a valuable therapeutic strategy for targeting METTL3‐EVL m6A axis‐mediated renal fibrosis." (PMID 37537731, 2023). "Hence, isoforsythiaside is a prospective METTL3 inhibitor for combating renal fibrosis and has potential translational value for clinical applications." (PMID 37537731, 2023). "Therefore, we hypothesised that METTL3 may act as a regulator of high uric acid‐induced renal fibrosis." (PMID 40100069, 2025). "Moreover, we explored whether the functional role of METTL3 in mitochondrial dysfunction and renal fibrosis occurs through the m6A modification of LONP1." (PMID 39261902, 2024). "Moreover, in both UUO and I/R‐induced renal fibrosis mice, METTL3 and corresponding m6A levels were consistently upregulated with the duration of disease, indicating a positive correlation of elevated METTL3 and m6A levels with the advancement of renal fibrosis." (PMID 37537731, 2023). "Hence, targeted regulation of METTL3 and the corresponding m6A may be a novel strategy to interfere with the HK‐2 cytofibrotic response and renal fibrosis." (PMID 37537731, 2023). "Therefore, METTL3 may drive obstructive renal fibrosis development by promoting miR‐21‐5p maturation." (PMID 34164910, 2021). "Furthermore, METTL3 catalysis of m6A modification may drive obstructive renal fibrosis development by promoting miR‐21‐5p maturation in mice." (PMID 34164910, 2021). "We first reveal that METTL3 facilitates M2‐driven MMT by modulating the TGF‐β1/Smad3 pathway, contributing to renal fibrosis in CAR." (PMID 39869489, 2025). "By using several experimental models (including mouse BMDMs, mouse CAR models, and human renal biopsy samples), this study demonstrates that METTL3 enhances Smad3 levels to facilitate M2‐driven MMT and renal fibrosis in CAR." (PMID 39869489, 2025). "Our findings establish a mechanistic link between METTL3 and renal allograft fibrosis, setting the stage for a shift in CAR management by integrating epigenetic regulation as a therapeutic approach to renal fibrosis." (PMID 39869489, 2025).
renal fibrosis (continued). "To elucidate the direct role of METTL3 in renal fibrosis during CAR, we utilized sham‐operated (named control group) and kidney transplantation mouse models with METTL3 wild‐type (named METTL3 WT group) and knockout (named METTL3 KO group)." (PMID 39869489, 2025). "Our research underscores the critical role of METTL3 in modulating TNF‐β/Smad3 signaling and its downstream effects on MMT and the development of renal fibrosis in CAR." (PMID 39869489, 2025). "On the basis of the specific interaction between METTL3 and LONP1, the ablation of METTL3 simultaneously reduced the methylation and protein levels of LONP1, accelerating renal fibrosis by maintaining mitochondrial homeostasis." (PMID 39261902, 2024). "Accordingly, we identified a novel METTL3 TCM monomer inhibitor, isoforsythiaside, and demonstrated that it significantly inhibited the METTL3/EVL m6A axis, thereby preventing renal fibrosis." (PMID 37537731, 2023). "After elucidating the underlying mechanism by which METTL3 modulates renal fibrosis, we investigated the function of an identified target gene of METTL3, namely, EVL, during renal fibrosis." (PMID 37537731, 2023). "Molecular docking and virtual screening with in vitro and in vivo experiments were applied to screen promising traditional Chinese medicine (TCM) monomers and explore their mechanism of regulating the METTL3/EVL m6A axis and anti‐renal fibrosis." (PMID 37537731, 2023). "Elevated METTL3 facilitated the m6A modification of EVL mRNA and promoted renal fibrosis by modulating TGF‐β1/Smad signal transduction." (PMID 37537731, 2023). "The m6A RNA methyltransferase METTL3 can enhance NSD2 mRNA stability and expression by YTHDF1 to alleviate renal impairment and renal fibrosis in DN." (PMID 35354439, 2022). "Our research is the first to demonstrate the role of the METTL3‐m6A‐miR‐21‐5p‐SPRY1/ERK/NF‐kB axis in obstructive renal fibrosis and provides a deeper understanding of renal fibrosis." (PMID 34164910, 2021). "Functional validation experiments demonstrated that silencing METTL3 using siRNA, genetic knockout, or treatment with the inhibitor STM2457 significantly reduced Smad3 expression, disrupted M2‐driven MMT, and alleviated renal fibrosis during CAR." (PMID 39869489, 2025). "Another study reported that METTL3 modifies m6A methylation on long-non-coding RNA (lncRNA) MALAT1 to upregulate MALAT1 expression, which thereby promotes transforming growth factor β1 (TGF-β1)-induced renal fibrosis through miR-145/FAK signaling." (PMID 37815911, 2024). "The present study shed light on the currently unclear mechanisms by which m6A modifications promote renal fibrosis, and the present findings suggest that the TCM monomer isoforsythiaside, which targets the overactivated METTL3/EVL m6A axis, is a potential strategy to prevent renal fibrosis." (PMID 37537731, 2023). "METTL3 has been shown to promote m6A modification of histone transferase NDS2 mRNA in mice and promote the stability of NSD2 mRNA through YTHDF1, subsequently inhibiting renal fibrosis and renal injury in DN mice." (PMID 38066436, 2023). "In TGF-β1-treated tubular epithelial cells, m6A modification exerts a regulatory role in positively regulating MALAT1 expression by engaging METTL3, suggesting the involvement of m6A modification in the MALAT1/miR-145/focal adhesion kinase (FAK) pathway of renal fibrosis." (PMID 37841018, 2023). "METTL3 facilitates miR-21-5p maturation, and miR-21-5p activates ERK/NF-κB signaling by suppressing sprouty RTK signaling antagonist 1 (SPRY1), which affects renal fibrosis progression." (PMID 37671161, 2023). "Simultaneously, we also found that METTL3 increases the modification of EVL m6A and regulates renal fibrosis through an IGF2BP2 dependent manner and proposed that the traditional Chinese medicine monomer Forsythia suspensa glycoside may be an inhibitor of METTL3 to alleviate chronic kidney disease." (PMID 40520008, 2025).
renal fibrosis (continued). "Even if this is not the first study for MALAT1 in renal fibrosis, our study indeed further revealed the role of MALAT1 in ON-induced renal fibrosis and the mechanism by which METTL3 positively regulates MALAT1." (PMID 32203053, 2020).
thyroid cancer (19 papers, 2019 to 2025). "With respect to histone modification, the METTL3-SETMAR-SMARCA2-TF axis is associated with thyroid cancer cell differentiation." (PMID 40819127, 2025). "In some cases of PTC, low METTL3 expression was observed, which was associated with the progression of thyroid cancer and poor prognosis." (PMID 40819127, 2025). "Previous studies of METTL3 in thyroid cancer have shown that reduced METTL3 expression is associated with a reduced response to immune checkpoint blockade." (PMID 38900084, 2024). "Furthermore, the METTL3‒PAX8‒YTHDC1 axis is linked to thyroid cancer dedifferentiation and progression, positioning it as a potential target for PTC treatment." (PMID 40819127, 2025). "Although these results indicate that METTL3 exerts contradictory effects on thyroid cancer, the precise underlying mechanism remains unclear." (PMID 34136491, 2021). "miR-493-5p targets METTL3, whose expression level correlates positively with the degree of thyroid cancer differentiation and whose low expression is closely associated with tumor progression and poor prognosis." (PMID 40530008, 2025). "A recent study revealed the role of the METTL3-SETMAR-SMARCA2-TF axis in the differentiation of thyroid cancer." (PMID 40819127, 2025). "This study revealed that METTL3-mediated m6A modifications (RNA modifications) maintain SETMAR mRNA stability via the m6A reader IGF2BP3 in well-differentiated thyroid cancer." (PMID 40819127, 2025). "Methyltransferase-like 3 (METTL3), an RNA m6A methylase that is silenced in thyroid cancer cells, promotes an immunosuppressive phenotype through CD70 demethylation." (PMID 40819127, 2025). "Several molecular pathways, such as the METTL3/c-Rel/IL-8 axis, ZC3H13/hsa_circ_0101050 axis, and ALKBH5/circNRIP1/PKM2 axis, are closely associated with thyroid cancer progression and poor prognosis." (PMID 40819127, 2025). "Significantly, the down-regulate of PAX8 can reverse the inhibitory effect of METTL3 on the proliferative ability of thyroid cancer." (PMID 38993572, 2024). "This work is the first to demonstrate the important function of the METTL3‐regulated epigenetic network in controlling the differentiation of thyroid cancer." (PMID 38900084, 2024). "In this study, we identified SETMAR as a differentiation‐related histone methylation modifier in thyroid cancer, and we found that its mRNA was stabilized by METTL3‐mediated m6A modification in an IGF2BP3‐dependent manner." (PMID 38900084, 2024). "In conclusion, we demonstrated that the control of thyroid differentiation‐related transcription factors via the METTL3‐SETMAR‐SMARCA2 axis contributes to the differentiation of thyroid cancer." (PMID 38900084, 2024). "MiR-21-5p is a tumorigenic miRNA targeting KLF3, YOD1, and METTL3, thus promoting pancreatic, hepatocarcinoma, and thyroid cancer progression and inducing chemoresistance." (PMID 39896803, 2024). "Although many studies have established a close relationship between METTL3 expression or m6A signature and malignant phenotypes, the potential role of METTL3 and m6A RNA modification in thyroid cancer is still largely elusive." (PMID 36232810, 2022). "Data about the role of METTL3 in thyroid cancer are few and elusive, but for the most part, they suggest an anticancer-like action." (PMID 36232810, 2022). "In conclusion, the study suggests that targeting METTL3 may influence the differentiation status of thyroid cancers, potentially making them more responsive to standard treatments such as chemotherapy and radioactive iodine." (PMID 39874138, 2025). "In thyroid cancer, programmed cell death protein 1 (PD-1) therapy resistance is mediated by tumor-associated macrophage (TAM)- derived EVs through the delivery of miR-21-5p, which inhibits methyltransferase-like 3 (METTL3)." (PMID 40806235, 2025).
thyroid cancer (continued). "Recently, M2-TAMs were shown to downregulate METTL3 in thyroid cancer cells and promote immunosuppressive TME through the transfer of extracellular vesicles (EVs), reversing the immunosuppressive effect of M2-TAMs that mediates resistance to anti-PD-1 therapy in thyroid cancer." (PMID 39941003, 2025). "Additionally, METTL3 knockdown in thyroid cancer cells enhances the secretion of pro‐inflammatory cytokines, particularly IL‐8, thereby promoting neutrophil infiltration." (PMID 41316520, 2025). "Similarly, in thyroid cancer, METTL3-regulated m6A modification enhances STTEAP1 mRNA stability in a YTHDF2-dependent manner, thereby inhibiting thyroid cancer cell proliferation, migration, and invasion." (PMID 38576024, 2024). "Finally, the METTL3‐14‐WTAP activator effectively facilitates the redifferentiation of thyroid cancer cells via the SETMAR‐SMARCA2‐TTF axis utilized." (PMID 38900084, 2024). "Through CCK8, colony formation assays, and transwell assays, we found that miR-493-5p mimic could rescue the inhibitory effect of METTL3 on the malignant behavior of thyroid cancer cells, including proliferative and migration ability." (PMID 38993572, 2024). "Additionally, by focusing on METTL3, we discovered a novel method for treating thyroid cancer differentiation, providing new therapeutic options for this disease." (PMID 38900084, 2024). "Finally, we evaluated the effectiveness of the METTL3‐14‐WTAP activator in treating thyroid cancer in vivo." (PMID 38900084, 2024). "In conclusion, the expression of SETMAR in thyroid cancer is stabilized by METTL3‐mediated m6A modification in an IGF2BP3‐dependent manner, which could explain its dysregulation during dedifferentiation of thyroid cancer." (PMID 38900084, 2024). "The results showed that METTL3 expression in thyroid carcinoma was significantly lower than that in normal thyroid tissue and was positively correlated with the differentiation level of thyroid carcinoma." (PMID 38993572, 2024). "Finally, we further determined whether METTL3 mediates malignant behavior of thyroid cancer cells dependent on PAX8 in vivo." (PMID 38993572, 2024). "In addition, we found that the dysregulation of SETMAR during thyroid cancer dedifferentiation is caused by a lack of METTL3‐mediated N6‐methyladenosine modification which maintains the stability of SETMAR mRNA." (PMID 38900084, 2024). "However, studies have also shown that METTL3 can induce the m6A mRNA modification of TCF1, a downstream effector of the classical Wnt pathway encoded by TCF7, by activating the Wnt pathway, thereby accelerating the progression of thyroid cancer." (PMID 34136491, 2021). "METTL3 regulates PAX8 expression via m6A modification, thereby affecting the differentiation and chemosensitivity of thyroid cancer cells." (PMID 40530008, 2025). "Typically, m6A modification tags CD70 mRNA for degradation; thus, METTL3 inhibition allowed CD70 mRNA to accumulate, resulting in increased CD70 protein expression in thyroid cancer cells." (PMID 39874138, 2025). "The METTL3-SETMAR-SMARCA2-TF axis unites RNA modifications, histone modifications, chromatin remodeling and accessibility to drive the differentiation of thyroid cancer." (PMID 40819127, 2025). "First, we synthesized levorotatory and dextral drug monomers of the METTL3‐14‐WTAP activator and examined their ability to induce thyroid cancer redifferentiation." (PMID 38900084, 2024). "More importantly, we utilized the METTL3‐14‐WTAP activator to restore SETMAR expression and promote the differentiation of thyroid cancer, thus providing a new method of redifferentiation therapy for treating patients with thyroid cancer." (PMID 38900084, 2024). "METTL3-14-WTAP activators can restore SETMAR expression, promoting thyroid cancer differentiation." (PMID 40819127, 2025).
thyroid cancer (continued). "In light of these results, we hypothesized that METTL3‐mediated m6A modifications are involved in controlling SETMAR expression and thus enhancing thyroid carcinoma differentiation." (PMID 38900084, 2024). "In addition, we found that METTL3 expression not only increased the levels of PAX8 but also inhibited the expression of NIS in tissue samples, which indicates that METTL3 relies on the expression of PAX8 to increase the sensitivity to chemotherapy drugs for thyroid cancer." (PMID 38993572, 2024). "However, despite these advances, traditional precision oncology approaches, which combine METTL3-14-WTAP activators and MAPK inhibitors, have not yet achieved satisfactory results in the treatment of thyroid cancer." (PMID 40819127, 2025).